MMP2 (matrix metallopeptidase 2)
Diseases named in the same sentence as MMP2 in open-access papers (continued):
Sharing a sentence is not in itself a finding about the gene and the disease.
abdominal aortic aneurysm (33 papers, 2005 to 2026). Enlargement and ballooning of the vessel that supplies arterial blood to the abdomen, pelvis and legs. "In particular, MMP-2, found in mesenchymal cells, has been linked to macrophage invasion and seems to be the elastase which has the highest tissular concentration in abdominal aortic aneurysms." (PMID 39408865, 2024). "Doxycycline (DOXY) is a well-established antibiotic that has recently shown potential in inhibiting matrix metalloproteinase-2 (MMP-2), a key enzyme involved in the progression of abdominal aortic aneurysms (AAA)." (PMID 41557116, 2026). "Statin therapy has also demonstrated efficacy in decreasing MMP-3 and MMP-9 levels in patients with abdominal aortic aneurysms, as well as MMP-2 and MMP-9 levels in individuals with arterial aneurysmal disease." (PMID 39200884, 2024). "This conclusion aligns with previous studies, such as the inhibition of NLRP3 inflammasome, coincident with the downregulation of MMP2 expression in the lesion site of abdominal aortic aneurysm (AAA), and the prevention of elastin degradation." (PMID 38992615, 2024). "Treatment with senolytic agents dasatinib and quercetin already showed effectivity against abdominal aortic aneurysm growth in aged mice infused with angiotensin II, where reduced expression of Mmp2 and Mmp9 was observed upon treatment." (PMID 38902222, 2024). "It has been found that MMP-2 from abdominal aortic aneurysm vascular smooth muscle cells has three times higher levels than in cells taken from tissues with atherosclerosis." (PMID 35745168, 2022). "Previous reports have identified that MMP-2, 9 and 25 upregulation are correlated with abdominal aortic aneurysm." (PMID 35223694, 2022). "The expression of MMP-2 has been reported in macrophages in abdominal aortic aneurysms and in alveolar macrophages in pneumothorax." (PMID 33441903, 2021). "SAA has been also shown to play a role in the formation of abdominal aortic aneurysm in an experimental mouse model by triggering matrix metalloproteinase 2 (MMP-2) activity and ensuing elastin degradation." (PMID 34534311, 2021). "A similar effect on the activation of both MMP–9 and MMP–2 proteins was found after application of quercetin in mice with abdominal aortic aneurysms." (PMID 32230721, 2020). "Various studies have demonstrated increases in the mRNA of MMP-2 in aTAA, as well as increased active MMP-2 after inducing ascending aortic aneurysms or abdominal aortic aneurysms in animals." (PMID 30794673, 2019). "Similarly, in the context of Trem-1−/− with angiotensin-II induced abdominal aortic aneurysm, inflammation and aortic wall degradation were markedly reduced, which was associated with decreased expression of Il1b, TNF-α, MMP2, and MMP9." (PMID 41226426, 2025). "In addition, SGLT2 inhibition prevents the development of abdominal aortic aneurysm in mice by limiting inflammation and MMP-2/9 expression by targeting specific upstream signaling pathways." (PMID 34445519, 2021). "The overexpression of MMP-2, -8, -9, and -12 was related to abdominal aortic aneurysm." (PMID 28977831, 2017). "FOSB expression in vascular smooth muscle cells (VSMCs) influences their phenotypic transformation, promoting MMP2/MMP9 expression, potentially accelerating abdominal aortic aneurysm (AAA) development." (PMID 40486911, 2025). "Increased proteolytic activity of MMP-2 and MMP-9 and consequent high circulating values of these MMPs have also been found in connection to abdominal aortic aneurysm rupture." (PMID 39408865, 2024). "In a mouse model of abdominal aortic aneurysm induced by intraluminal elastase and extraluminal calcium chloride exposure in vivo, TG2, TNF-α, MMP-2, and MMP-9 mRNA expression were increased in the acute phase compared to the chronic phase of the disease." (PMID 39744707, 2024).
abdominal aortic aneurysm (continued). "Throughout the progression of abdominal aortic aneurysm (AD), there is an upregulation in the degradation of the ECM and the expression of ECM enzymes, notably including MMP-9, MMP-2, and ADAMTs." (PMID 37836434, 2023). "The results conclude that oral administration of sitagliptin can prevent abdominal aortic aneurysm formation in Ang II-infused apoE-/-mice, at least in part, by increasing of GLP-1 activity, decreasing MMP-2 and MMP-9 production from macrophage infiltration." (PMID 25876091, 2015). "Glutamine protected against mouse abdominal aortic aneurysm through inhibiting M1 macrophage activation, secretion of IL-6 and TNF-α by macrophage, release of MMP-9 by RAW264.7 (macrophage) and MMP-2 by MOVAS (SMC), as well as apoptosis of vascular SMC by ROS and MMP." (PMID 38903916, 2024). "TG2 has been shown to inhibit MMP-2, -9, and tumor necrosis factor (TNF)-α in primary cultures of human abdominal aortic aneurysm-derived smooth muscle cells, supporting the notion that TG2 stabilizes the ECM and prevents the progression of abdominal aortic aneurysm." (PMID 39744707, 2024). "It has also been reported that green tea phenol and tanshinone, a natural extract of Salvia miltiorrhiza, can effectively inhibit MMP-2 and MMP-9 activity to reduce the development of abdominal aortic aneurysms and that tanshinone has a better safety profile than doxycycline." (PMID 35463768, 2022). "In addition, a recent study noted that knockdown of PVT1 decreased levels of MMP-2 and MMP-9, augmented TIMP-1 expression, and suppressed serum levels of TNF-α, IL-1β, and IL-6 in VAMC and ApoE-/- mice of abdominal aortic aneurysm model." (PMID 34775377, 2021). "Moreover, several authors have identified increased levels of VEGF, MMP-2, and MMP-9 in the blood of patients with abdominal aortic aneurysms." (PMID 34572455, 2021). "Based on these results, we confirmed that zinc treatment could suppress the inflammation and the expression of MMP-2 and MMP-9 in abdominal aortic aneurysm." (PMID 26918963, 2016). "A study found that both MMP-2 knocked-out mice and MMP-9 knocked-out mice failed to develop abdominal aortic aneurysms (AAA) in a AAA mouse model, indicating that MMPs played a key role in aneurysmal diseases." (PMID 35045850, 2022).
diabetic nephropathy (33 papers, 2014 to 2026). "In studies in patients with diabetic nephropathy, the administration of vitamin E caused a reduction in the serum concentration of MMP-2, MMP-9, and TNF-α, while zinc was shown to decrease the Cd-induced expression of MMP-1 in synoviocytes." (PMID 32927885, 2020). "In addition, in animal models, MMP-2 has been shown to induce renal tubular cell epithelial-mesenchymal transformation, which could cause tubulointerstitial fibrosis in diabetic nephropathy." (PMID 25143788, 2014). "On the contrary, polymorphisms such as rs243865, which reduce Mmp2 expression, are associated with impaired ECM remodeling and tissue repair, contributing to diseases such as diabetic nephropathy, pulmonary fibrosis, and chronic wounds." (PMID 39769454, 2024). "Diabetic nephropathy (DN) patients had a significant reduction in serum levels of MMP2, TIMP1 and TIMP2 compared to the controls." (PMID 37445827, 2023). "Clinical studies of diabetic nephropathy and kidney transplantation outcomes showed that M2-macrophages localized at the fibrotic areas and actively produced MMP-2/9." (PMID 35629404, 2022). "In patients with diabetic nephropathy, which represents the leading cause of CKD progression to date, increased blood and urinary levels of MMP-2, -7, -8, -9, and NGAL have been reported." (PMID 33573220, 2021). "The antibiotic doxycycline inhibits the activity of MMP-2 and -9 and has been shown to reduce proteinuria in patients with diabetic nephropathy." (PMID 33573220, 2021). "Altered expression of the gelatinases MMP-2 and MMP-9 has been associated with various glomerulopathies characterised by GBM defects, including diabetic nephropathy and Alport syndrome." (PMID 29167507, 2017). "The expression of both isoforms of MMP-2 was enhanced in an experimental model of diabetic nephropathy and in human diabetic nephropathy." (PMID 28178341, 2017). "Some studies confirmed that the activity and abundance of MMP-2 and MMP-9 decreased in the early stage of diabetic nephropathy; therefore, renal function damage may be related to the decrease in MMP-2 and MMP-9 activities." (PMID 34819020, 2021). "The participation of both MMP-2 isoforms was also examined in diabetic nephropathy." (PMID 33732288, 2021). "Finally, an increase in both MMP-2 isoforms was found in renal biopsies of patients with diabetic nephropathy." (PMID 33732288, 2021). "However, in a diabetic nephropathy model, MMP2 knockout mice showed increased collagen deposition and fibroblast activation suggesting an anti-diabetic and anti-fibrotic role of MMP2." (PMID 29464020, 2018). "Moreover, the presence of diabetic nephropathy had a significant impact on the MMP-2/TIMP-2 system." (PMID 38610612, 2024). "Our work suggests that selective targeting of the two MMP-2 isoforms could represent a potential novel therapeutic approach for the prevention or treatment of diabetic nephropathy, in addition to the recognized approaches of stringent control of blood glucose and lipids." (PMID 28178341, 2017). "In patients with diabetic nephropathy, selenium supplementation decreased markers like hs-CRP, MMP-2, and MDA." (PMID 41393951, 2025). "In this group, we showed a significant increase in the concentration of MMP-2 and TIMP-2 in diabetic nephropathy, which is consistent with the results of previous studies." (PMID 38610612, 2024). "MMP-2 and MMP-9 are two of the proteinases that have been widely studied in human diabetic kidney disease." (PMID 35629404, 2022). "Compared with the normal control group, the mRNA expression of MMP-2 and MMP-9 was significantly reduced in diabetic nephropathy group." (PMID 30823598, 2019). "Estradiol did not cause podocyte apoptosis preceding glomerulosclerosis, which was shown in the estrogen receptor (ER)-knockout mouse model, reduced albuminuria, TF progression and glomerulosclerosis by suppressing the activity of MMP-2 and MMP-9 in diabetic nephropathy." (PMID 35629404, 2022).
diabetic nephropathy (continued). "An imbalance between MMP2 and TIMP2 contributes to ECM accumulation and fibrosis in diabetic nephropathy, an effect that may be mediated at least in part by TGF-β, which was also dysregulated in the present study." (PMID 32787975, 2020). "MMP-2 is also described as related to diabetic kidney disease, which was not reflected in the current study." (PMID 31936869, 2020).
esophageal squamous cell carcinoma (33 papers, 2007 to 2026). Esophageal squamous cell carcinoma (ESCC) is a type of esophageal carcinoma (EC) that can affect any part of the esophagus, but is usually located in the upper or middle third. "Previous studies by our team have uncovered the irreplaceable role of DCLK1-S in the development of esophageal squamous cell carcinoma by stimulating the MAPK/ERK/MMP2 pathway to promote the EMT process." (PMID 38980538, 2024). "The C→T transitions at -1306 and -735 in the MMP-2 promoter eliminate a Sp1-binding site (CCACC box), thereby decreasing MMP-2 transcription and increasing the risk of esophageal squamous cell carcinoma (OR = 6.53; 95% CI = 2.78–15.33)." (PMID 29299175, 2017). "For MMP2, a case–control study showed that patients with esophageal squamous cell carcinoma carrying the −1306 CC or −735 CC genotypes had an increased risk of developing cancer." (PMID 25906101, 2015). "In esophageal squamous cell carcinoma cells, Aurora-A overexpression induces cell migration and invasion as well as secretion and expression of matrix metalloproteinase-2 (MMP-2)." (PMID 26779440, 2015). "MMP2 and MMP9 are two important members of the MMP family, and overexpression of MMP2 and MMP9 has been confirmed to associate with a variety of malignancies that contain esophageal squamous cell carcinomas." (PMID 24885858, 2014). "Finally, increased expression of ATF4 in esophageal squamous cell carcinoma correlates with invasion and metastasis, an effect attributed to increased transcription of MMP-2 and MMP-7." (PMID 27802179, 2016). "For MMP2, a case-control study showed that patients with esophageal squamous cell carcinoma carrying the -1306CC or -735CC genotypes had an increased risk of developing cancer (odds ratio (OR) = 1.52, 95% confidence interval (CI) = 1.17–1.96; and OR = 1.30, 95% CI = 1.04–1.63 respectively)." (PMID 17958893, 2007). "Meanwhile, activated-STAT3 also can regulate MMP2 gene transcription via binding to MMP2 promoter in esophageal squamous cell carcinoma (ESCC), leading to ESCC metastasis." (PMID 38560562, 2024). "In cases of esophageal squamous cell carcinoma (ESCC), silencing circ_0046534 has been shown to inhibit the growth and metastasis of ESCC via the miR-339-5p/MMP2 pathway." (PMID 38816365, 2024). "RNF128 regulates the expression of MMP-2 by activating the EGFR/MAPK signaling pathway, thereby promoting the invasion and metastasis of esophageal squamous cell carcinoma." (PMID 38143380, 2023). "In esophageal squamous cell carcinoma, pharmacological inhibition of PAK1 reduces cancer cell migration and invasion as well as matrix metalloproteinase (MMP)-2 and MMP-9 expression." (PMID 38188678, 2023). "In esophageal squamous cell carcinoma (ESCC), overexpression of ATF4, a PERK effector, is involved with increased expression of MMP-2 and MMP-7 to promote invasion and metastasis of ESCC in vitro and in vivo." (PMID 33746610, 2021). "In esophageal squamous cell carcinoma, the overexpression of RNF128 promotes signaling through the EGFR/MAPK/MMP-2 pathway to enhance cell invasion and metastasis." (PMID 33962392, 2021). "Moreover, the knockdown of the Nrf2 by short hairpin RNA (shRNA) in esophageal squamous cell carcinoma (ESCC) suppressed the expression of MMP-2 and enhanced E-cadherin mRNA levels, resulting in a decreased invasion and migration of cancer cells." (PMID 26697129, 2016). "Since it has been shown that S100A4 regulates the expression of invasion- and migration-associated genes, such as metalloproteases (MMPs), we next analyzed the mRNA levels of MMP2, which is known to be regulated by S100A4 in esophageal squamous cell carcinoma." (PMID 25738360, 2015). "The HMGA2 protein is a non-histone chromatin factor involved in DNA repair, aggressiveness of esophageal squamous cell carcinoma, epithelial-to-mesenchymal transition (EMT) process, and the up-regulation of EMT-related genes such as TGF-beta, SNAIL1, SLUG, MMP2, and MMP9 in RMS patients." (PMID 36139434, 2022).
esophageal squamous cell carcinoma (continued). "This study analyzed miRNA pathway enrichment derived from tumor-normal mRNA differential expression in esophageal squamous cell carcinoma (ESCC) patients and investigated whether Ilomastat, a known MMP inhibitor, could plausibly bind the catalytic site of MMP-2." (PMID 42158110, 2026). "However, MMP2 and MMP9 are inhibited by miR-34a-5p in esophageal squamous cell carcinoma." (PMID 30696040, 2019). "Also, the overexpression of miR-34a significantly inhibited the migratory and invasive potential of esophageal squamous cell carcinoma (ESCC) cells via inhibition of FNDC3B (Fibronectin Type III Domain Containing 3B), MMP2 (matrix metalloproteinase-2) and MMP9 expression levels." (PMID 29036883, 2017).
glaucoma (33 papers, 2008 to 2025). Increased pressure in the eyeball due to obstruction of the outflow of aqueous humor. "Multiple regression analysis revealed that the presence of preoperative glaucoma was the independent risk factor affecting MMP2 levels." (PMID 41009516, 2025). "In Polish patients with POAG, MMP2 rs243865 TT and rs2285053 TT genotypes were associated with rim area in early glaucoma, suggesting a protective role in disease progression." (PMID 39769228, 2024). "Another study conducted with Polish patients with POAG found that the MMP2 735TT and -1306TT genotypes were significantly associated with a larger rim area (early glaucoma), suggesting a protective role against POAG." (PMID 39769228, 2024). "Preoperative glaucoma was found to be associated with MMP2 levels." (PMID 41009516, 2025). "We therefore postulate that the mechanisms underlying RGC death in the NMDA-induced glaucoma model and in the optic nerve ligation/crush models are very distinct and that MMP-2 and MMP-9 are apparently differentially involved in these different types of glaucomatous injury." (PMID 26451076, 2015). "Increased MMP Expression in Glaucoma: Numerous studies have reported that glaucoma patients exhibit elevated levels of specific matrix metalloproteinases (MMPs), particularly MMP-2 and MMP-9, within the aqueous humor and trabecular meshwork." (PMID 40698094, 2025). "Our observation of decreased expression of hsa-miR-451a in AH of glaucoma patients is in line with previous reports of increased expression of MMP2 in AH." (PMID 34156425, 2021). "The ECM remodeling includes increased deposition of collagens, loss of elastin structure, and higher transforming growth factor-β2 (TGF-β2) and matrix metalloproteinase-2 (MMP-2) protein levels in human glaucoma LC tissue." (PMID 33375386, 2020). "Chelation of MMP2 bound Zn2+ by application of topical carbonic anhydrase inhibitors has served as a biological exploitation in lowering intraocular pressure in glaucoma patients." (PMID 32204514, 2020). "In contrast, our results revealed attenuated RGC death in MMP-2 null animals exposed to yet another glaucoma model, that is, excitotoxic RGC death induced by an intravitreal injection of NMDA." (PMID 26451076, 2015). "In this study, we sought to determine the spatiotemporal expression profile of MMP-2 in the excitotoxic retina and to unravel its role during glaucoma pathogenesis." (PMID 26451076, 2015). "MMP1, MMP2, and MMP9 have previously been implicated in the pathogenesis of primary open angle glaucoma (POAG) and open angle glaucoma secondary to exfoliation syndrome (XFG), respectively." (PMID 20808730, 2010). "Furthermore, the presence of preoperative glaucoma was associated with higher levels of TIMP2 and MMP2." (PMID 41009516, 2025). "We found that the levels of TIMP1 and MMP2 were higher in patients with glaucoma." (PMID 41009516, 2025). "Furthermore, TIMP1 and MMP2 levels were significantly elevated in patients with preoperative glaucoma." (PMID 41009516, 2025). "For example, in a mouse model of glaucoma, reducing ER stress could reduce intraocular pressure by inhibiting the activity of MMP2." (PMID 37907982, 2023). "Further studies are needed to elucidate the role of MMP2 in scleral remodeling, which might bring up new therapeutic avenues to prevent the progression of glaucoma." (PMID 32719611, 2020). "Interventions to modulate the scleral ECM remodeling may provide a new approach for glaucoma therapy, and MMP2 may be used as a potential novel therapeutic target." (PMID 32719611, 2020). "Luminex analysis of AqH samples revealed significantly elevated levels of MMP-2, MMP-3, ET-1, sEMMPRIN, ZAG, sLOX-1, follistatin, cortisol, endostatin, sTIE-2, and PDGF-BB in glaucoma participants (adjusted p < 0.05)." (PMID 41154592, 2025). "The levels of TNF-α, MMP-2, MCP-1, IFN-γ, TIMP-1, IL-6, IL-8, VEGF, and LT-α were different among the three types of glaucoma." (PMID 36254076, 2022).